RNF8 (ring finger protein 8)
Diseases named in the same sentence as RNF8 in open-access papers (continued):
Sharing a sentence is not in itself a finding about the gene and the disease.
autism (2 papers, 2017 to 2023). Persistent deficits in social interaction and communication and interaction as well as a markedly restricted repertoire of activity and interest as well as repetitive patterns of behavior. "HERC2 interacts with the autism-linked ubiquitin ligase RNF8/UBC13 and the scaffold protein NEURL4, taking part in a novel cytoplasmic ubiquitin-signalling network that suppresses synapse formation in the brain." (PMID 37307281, 2023). "Because deregulation of neuronal connectivity is thought to contribute to autism, we assessed the potential role of the autism-linked ubiquitin ligase RNF8 in synapse development in the cerebellum." (PMID 29097665, 2017). "Interaction proteomics analyses reveal that RNF8 forms a complex with the autism-linked HECT domain protein HERC2 and scaffold protein Neuralized 4 (NEURL4)." (PMID 29097665, 2017).
hepatocellular carcinoma (2 papers, 2022 to 2023). A malignant tumor that arises from hepatocytes. "In hepatocellular carcinoma, Trabid inhibits cancer growth and metastasis by cleaving RNF8-induced K63-linked ubiquitination of Twist." (PMID 35831895, 2022).
leukaemia (2 papers, 2016 to 2020). "In this vein, it is interesting to note that RNF8 deficiency occurs in ATL of all types, suggesting that it likely emerges early during leukemia development." (PMID 32453758, 2020).
lung adenocarcinoma (2 papers, 2013 to 2022). A carcinoma that arises from the lung and is characterized by the presence of malignant glandular epithelial cells. "In addition, significant downregulation of RNF8 was observed in kidney chromophobe (KICH), kidney renal papillary cell carcinoma (KIRP), lung adenocarcinoma (LUAD), prostate adenocarcinoma (PRAD) and thyroid carcinoma (THCA)." (PMID 35831895, 2022).
melanoma (2 papers, 2016 to 2023). A malignant, usually aggressive tumor composed of atypical, neoplastic melanocytes. "In this study, we found that the infiltration of fewer immune cells in melanoma-beared RNF8 deficient host compared with the control host, including CD4+ T, CD8+ T, and NK cells." (PMID 37391451, 2023). "S100 and HMB45 positive cells in melanoma were enhanced in RNF8−/− mice, which implied that RNF8 deficiency in TME promoted melanoma progression." (PMID 37391451, 2023). "RNF8 deficiency in the host but sufficiency in implanted melanoma results in immune exclusion and tumor progression due to the upregulation of gal-3." (PMID 37391451, 2023). "RNF8 affects DNA damage response by inducing G2/M checkpoint activation, and downregulation of the G2/M checkpoint gene was significantly associated with prolonging progression-free survival with immune checkpoint inhibitors therapy and aided in the treatment of melanoma." (PMID 37391451, 2023). "Results showed that long-term treatment with LAC delayed melanoma growth and progression in both RNF8+/+ and RNF8−/− groups." (PMID 37391451, 2023). "Subsequently, we detected the immune cell infiltration of melanoma in RNF8+/+ and RNF8−/− mice by mass cytometry (CyTOF)." (PMID 37391451, 2023). "The t-SNE analysis was presented for visualized observation of the immune cell populations changes of LAC treated melanoma in RNF8+/+ and RNF8−/− group." (PMID 37391451, 2023). "In this study, we demonstrated that RNF8 deficiency induced gal-3 high expression in TME, and accelerated melanoma growth with a deteriorated TME." (PMID 37391451, 2023). "Based on the remarkable distribution and expression difference of IL-12 and IFN-γ in melanoma particular in RNF8−/− mice, we investigated ubiquitination modifications omics data of control and RNF8-knockdown cells." (PMID 37391451, 2023). "In-depth analysis of immune cells by t-SNE identified CD3+ T cells, CD3+ CD4+ T cells, CD3+ CD8+ T cells and NK cells clusters, moreover, these clusters were decreased in melanoma-beared RNF8−/− mice." (PMID 37391451, 2023). "Knockout of RNF8 in host mice significantly accelerated the progression of melanoma." (PMID 37391451, 2023). "The IL-12 and IFN-γ expression in melanoma from RNF8−/− mice were reduced." (PMID 37391451, 2023). "IHC staining of CD3+ T cells infiltration in melanoma was increased after LAC intervention, particularly in RNF8−/− mice, which performed fewer immune cells infiltration in TME." (PMID 37391451, 2023). "By exploring the RNF8/gal-3/cytokine axis action in TME, we acquired a better understanding of tumor immune exclusion and designed an effective combination therapeutic strategy for melanoma." (PMID 37391451, 2023). "We investigated the regulation mechanism of immune exclusion by RNF8 mediated gal-3 ubiquitination via ubiquitin-proteasome system in TME, and the effect of gal-3 inhibition combined with immune checkpoint inhibitor treatment on melanoma." (PMID 37391451, 2023).
prostate carcinoma (2 papers, 2022 to 2023). A carcinoma that arises from epithelial cells of the prostate gland. "Therefore, it can be predicted that hsa_circ_0005692/miR-214-3p/RNF8 may serve as one of the competing endogenous RNA (ceRNA) networks in prostate cancer, and it is of great significance to study the function and role of hsa_circ_0005692 in prostate cancer." (PMID 38040819, 2023).
viral infection (2 papers, 2011 to 2020). "In conclusion, both RNF8 dysregulation by Tax during viral infection and RNF8 down-regulation during chronic infection and progression to disease promote DDR impairment and genomic instability of ATL." (PMID 32453758, 2020). "We observed that a) both viruses were transcriptionally repressed by RNF8, b) this repression was more significant in the absence of ICP0 and c) RNF8-mediated repression decreased over time during wild-type but not ICP0-null virus infection, presumably as a consequence of RNF8 degradation." (PMID 21698222, 2011).
Alzheimer disease (1 paper, 2022). A progressive, neurodegenerative disease characterized by loss of function and death of nerve cells in several areas of the brain leading to loss of cognitive function such as memory and language. "Interestingly, in our KEGG enrichment analysis, we noticed is that RNF8 was involved in many neurodegenerative diseases, such as Parkinson's disease, Alzheimer's disease, and amyotrophic lateral sclerosis." (PMID 35831895, 2022).
autism spectrum disorder (1 paper, 2017). A spectrum of developmental disorders that includes autism, and Asperger syndrome. "Whether RNF8 function in suppression of synapse formation is relevant to the pathogenesis of autism spectrum disorder is an interesting question for future studies." (PMID 29097665, 2017).
Azoospermia (1 paper, 2021). Absence of any measurable level of sperm,whereby spermatozoa cannot be observed even after centrifugation of the semen pellet. "Up-regulation of RNF8 can predict the presence of sperm in individuals with azoospermia." (PMID 34828386, 2021).
B-cell lymphomas (1 paper, 2013). "Recent data has indicated that Rnf8 also functions as a tumor suppressor, and that about 40% of Rnf8-deficient mice develop tumors, mostly thymic and B-cell lymphomas." (PMID 23382699, 2013).
endothelial dysfunction (1 paper, 2025). In vascular diseases, endothelial dysfunction is a systemic pathological state of the endothelium (the inner lining of blood vessels) and can be broadly defined as an imbalance between vasodilating and vasoconstricting substances produced by (or acting on) the endothelium. "With this approach, we revealed translational regulation of SND1 as a key mediator of sunitinib-induced endothelial dysfunction, which suggests that targeting SND1 translation and the SND1 downstream factors UBE2N, RNF8, and RNF168 is a potential therapeutic strategy for vascular dysfunction." (PMID 39895626, 2025). "Furthermore, wound-healing assays revealed that the protective effects of UBE2N OE on sunitinib-induced endothelial dysfunction were reversed by inhibition of RNF8 or RNF168 but not HLTF and SHPRH." (PMID 39895626, 2025).
esophageal squamous cell carcinoma (1 paper, 2021). Esophageal squamous cell carcinoma (ESCC) is a type of esophageal carcinoma (EC) that can affect any part of the esophagus, but is usually located in the upper or middle third. "For example, corilagin targeting RNF8 effectively inhibits cell proliferation of esophageal squamous cell carcinoma (ESCC) and induces apoptosis." (PMID 33912571, 2021).
gastric cancer (1 paper, 2016). A primary or metastatic malignant neoplasm involving the stomach. "If RNF8 is also upregulated in other cancer types and if the affected organ is also anatomically accessible, such as the stomach in gastric cancer, therapeutic adenoviral vectors can be perfused or injected under direct visualization using an endoscope." (PMID 26788910, 2016).
herpesvirus infection (1 paper, 2011). "This study highlights important parallels between recognition of cellular DNA damage and recognition of viral genomes, and adds RNF8 and RNF168 to the list of factors contributing to the intrinsic antiviral defense against herpesvirus infection." (PMID 21698222, 2011).
liver cancer (1 paper, 2023). An epithelial or non-epithelial malignant neoplasm that arises from the liver. "It was also found that RNF8 protein was more abundant in liver cancer cell lines than in the hepatic normal cell line." (PMID 37154586, 2023). "Based on the existing information, we wondered whether RNF8 could alter therapeutic effects in liver cancer." (PMID 37154586, 2023). "Therefore, our experiments provide clues for the clinical application of RNF8 as a prognostic marker and a therapeutic target for liver cancer." (PMID 37154586, 2023). "Kaplan‒Meier survival analysis showed that higher RNF8 expression was associated with worse overall survival (OS,P=0.0041), worse disease-specific survival (DSS,P=0.0037), worse progression-free survival (PFS,P=0.0099) and worse relapse-free survival (DFS,P=0.0057) in liver cancer patients." (PMID 37154586, 2023). "In this study, based on clues from public databases showing up-regulated expression of RNF8 in HCC tissues and its relationship with poor prognosis in liver cancer, we performed experiments in HCC cell lines and patient tissues." (PMID 37154586, 2023). "In summary, we confirmed that knockdown ofRNF8 inhibited EMT and increased drug sensitivity in liver cancer cells, and we also proposed that there was a close relationship between the impacts of RNF8 on EMT and the role of RNF8 in drug sensitivity." (PMID 37154586, 2023). "Thus, inhibition of RNF8 increased sensitivity in liver cancer cells with a poor response to sorafenib but had no impact on cells with a good response, which further supported that RNF8 played a critical role in sorafenib tolerance." (PMID 37154586, 2023).
lymph node metastasis (1 paper, 2016). "Furthermore, RNF8 is aberrantly expressed in invasive breast cancer and positively correlates with lymph node metastasis." (PMID 27259701, 2016).
lymphoma (1 paper, 2013). A malignant (clonal) proliferation of B- lymphocytes or T- lymphocytes which involves the lymph nodes, bone marrow and/or extranodal sites.
lymphopenia (1 paper, 2013). Reduction in the number of lymphocytes.
male infertility (1 paper, 2025). The inability of the male to effect fertilization of an ovum after a specified period of unprotected intercourse. "To further clarify the exact mechanism of RNF8 gene deletion leading to male infertility, we conducted scRNA-seq analysis on the testicular tissues of RNF8+/+ (WT) and RNF8−/− (KO) mice to explore the effects of RNF8 deficiency on mice testis." (PMID 40707433, 2025). "In this study, we observed an increase in pro-inflammatory macrophages within the testes of RNF8−/− mice, and we noted that the pro-inflammatory macrophages were particularly elevated in patients with oligospermia, prompting us to investigate their role in male infertility." (PMID 40707433, 2025).
memory impairment (1 paper, 2019). "Importantly, Rnf8-deficient neurons appear more susceptible to X-ray-induced DNA damage and Rnf8-deficient mice display memory impairment and reduced exploratory behavior in the open-field test." (PMID 31623112, 2019).
nasopharyngeal carcinoma (1 paper, 2021). A carcinoma arising from the nasopharyngeal epithelium. "Moreover, RNF8 (ring finger protein 8) protein catalyzes the mono-ubiquitination of histones H2A and H2B during DNA damage, thereby facilitating DNA damage repair and activation of cell cycle checkpoint; RNF8 is associated with radioresistance in human nasopharyngeal cancer cells." (PMID 33898418, 2021).
Nijmegen breakage syndrome (1 paper, 2012). Nijmegen breakage syndrome is a rare genetic disease presenting at birth with microcephaly, dysmorphic facial features, becoming more noticeable with age, growth delay, and later-onset complications such as malignancies and infections. "These include ATM, NBS1 (nibrin, which is encoded by a gene mutated in Nijmegen Breakage Syndrome) and RNF8 (RING finger protein 8)." (PMID 23050241, 2012).
non-small cell lung carcinoma (1 paper, 2016). A group of at least three distinct histological types of lung cancer, including non-small cell squamous cell carcinoma, adenocarcinoma, and large cell carcinoma. "We retrospectively analyzed 71 paraffin-embedded tumor samples from advanced non-small-cell lung cancer patients treated with first-line platinum based chemotherapy and measured the mRNA expression levels of BRCA1, RNF8, UBC13 and HERC2 using real-time PCR." (PMID 27179511, 2016).
osteoma (1 paper, 2013). A benign, well-circumscribed, bone-forming neoplasm predominantly composed of lamellar bone.
cancer (33 papers, 2010 to 2025). A tumor composed of atypical neoplastic, often pleomorphic cells that invade other tissues. "Studies have shown that RNF8 is also involved in many cancer-associated biological processes such as tumorigenesis and cancer metastasis." (PMID 35831895, 2022). "First, to reveal the expression pattern in different cancer types, the expression of RNF8 was analyzed in pancancer tissues and associated normal tissues." (PMID 35831895, 2022). "Despite the emerging understanding of the biological function of RNF8 in cancers, the underlying molecular mechanism of how RNF8 and its interactome network regulate divergent pathways and phenotypes is needed." (PMID 35831895, 2022). "It has been reported that RNF8 causes genomic instability, tumorigenesis, and malignant tumors when RNF8 exceeds appropriate levels and accumulates excessively." (PMID 33912571, 2021). "As expected, the cisplatin sensitivity induced by si-RNF8 was significantly compromised by a pan-caspase inhibitor z-VAD-fmk (20 μM) or si-Caspase-3 in BIN1-deficient cancer cells." (PMID 34948122, 2021). "Loss of RNF8 function can sensitize cells to both IR and DNA damage-inducing agents including anti-cancer drugs." (PMID 27259701, 2016). "Consistent with its role in DSB signaling and repair, loss of Rnf8 leads to increased genomic instability and cancer risks." (PMID 23382699, 2013). "Mice deficient for Mdc1, Rnf8, 53bp1 or Brca1 have increased cancer susceptibility likely due to their elevated levels of genomic instability." (PMID 21552324, 2011). "Remarkably, Rnf8-/- mice are growth retarded and display increased cancer predisposition, demonstrating that Rnf8 is a novel tumor suppressor." (PMID 21054854, 2010). "In addition, our functional analysis of RNF8 in different cancers implied that RNF8 might be associated with the function of immune cells, these data quickly attracted our interest." (PMID 35831895, 2022). "Our work provides a unique framework for researchers and clinicians who seek to better explore or understand RNF8-regulated biological functions in cancers and diseases." (PMID 35831895, 2022). "Pivoted on the actual role in cancer development, a study has once recorded that induction of c-Myc expression facilitates RING finger protein 8 to promote CC cell proliferation." (PMID 34623601, 2022). "We noticed that the role of RNF8 in tumorigenesis, metastasis, and chemoresistance has been increasingly reported in many cancers recently." (PMID 35831895, 2022). "This study will hopefully facilitate the rational design and further development of anti-RNF8 therapy in cancers." (PMID 35831895, 2022). "Based on microarray staining data from The Human Protein Atlas, 75% of the PC samples show high/medium expression of RNF8, which is the highest staining frequency among several cases of cancers." (PMID 35428760, 2022). "The results showed that the correlation between RNF8 and tumor infiltration varied in different cancers." (PMID 35831895, 2022). "Our work provides a unique framework for researchers and clinicians who seek to better explore or understand RNF8-regulated biological functions in cancers." (PMID 35831895, 2022). "The distinct and critical roles of RNF8 in tumorigenesis, cancer progression and resistance to chemotherapy are found both in our results and many previous reports." (PMID 35831895, 2022). "Taken together, these results further demonstrated the connection between RNF8 and clinical parameters in different cancers." (PMID 35831895, 2022). "Multiple previous studies have demonstrated that RNF8 regulates the progression and metastasis of cancer cells in different cancers." (PMID 35831895, 2022).